U3 (Small nucleolar RNA U3 )
Synonyms: LOC124904983
Gene: Small nucleolar RNA gene on chromosome 20 (3,384,229 to 3,384,440, forward strand). Ensembl gene ENSG00000201346.
Gene Ontology:
Biological process: RNA processing
Cellular component: nucleolus
Homologues: Orthologues: chimpanzee U3 (99% identical), macaque U3 (92% identical). Paralogues in human: U3 (86% identical), U3 (83% identical), SNORD3P1 (83% identical), U3 (81% identical), SNORD3E (81% identical), SNORD3G (81% identical), U3 (80% identical), U3 (79% identical), U3 (78% identical), U3 (77% identical), U3 (76% identical), SNORD3D (76% identical), and 15 more.